APOE (apolipoprotein E)
Diseases named in the same sentence as APOE in open-access papers (continued):
Sharing a sentence is not in itself a finding about the gene and the disease.
dyslipidemia (continued). "Therefore, the association between APOE polymorphism and dyslipidemia was further adjusted for obesity-related traits (BMI, WC, HC, and WHR)." (PMID 27724906, 2016). "Therefore, we focused on two key questions: (i) Are APOE rs429358 and rs7412 polymorphisms significantly associated with lipid profiles and dyslipidemia in Vietnamese children?" (PMID 27724906, 2016). "Logistic models adjusting for age, gender, APOE genotype, body mass index, alcohol consumption, smoking, physical activity, medication use for cardiovascular diseases were used to examine the relationship between selenium levels and the risk of dyslipidemia." (PMID 26380972, 2015). "Furthermore, obesity is associated with an increased risk of dyslipidemia in ApoE2/4 carriers similar to what can be observed for other ApoE genotypes." (PMID 26605088, 2015). "In summary, the possible pathogenesis of preeclampisa is inflammation caused by the dyslipidemia through the knockout of apoE, and the dysfunction of iNOS could contribute to exacerbation of preeclampsia." (PMID 23472151, 2013). "One explanation for this observation may be that the dyslipidemia of ApoE deficient mice is mainly due to remnant lipoproteins of intestinal origin." (PMID 24324578, 2013). "So we proposed that the dyslipidemia related to the apoE may be associated with the pathogenesis of preeclampisa, and iNOS may be involved in the mechanism." (PMID 23472151, 2013). "APOE genotypes are associated with lipid levels in patients with RA, and may contribute to dyslipidemia in some patients." (PMID 23613766, 2013). "One commonly used mouse model of dyslipidemia is the apolipoprotein E-deficient (apoE-/-) mouse, which exhibits the typical features of dyslipidemia seen in humans, including elevations in LDL cholesterol and triglyceride levels and reductions in HDL cholesterol levels." (PMID 22204493, 2011). "In addition to metabolic syndrome and AD associated with lipid and Aβ metabolism, ApoE glycosylation and sialylation may pose an influence on the development of other diseases as well." (PMID 39169951, 2024). "Additionally, rs117026536 in the LPL gene, rs651821 in the APOA5 gene, rs9926440 in the CETP gene, and rs429358 in the APOE gene were associated with dyslipidemia.The GWAS analysis of the male subjects revealed 13 significant SNPs in the discovery stage (P < 5 × 10− 8)." (PMID 36419087, 2022). "To estimate the associations between the APOE allele carrier status and the at-risk levels of dyslipidemia in the middle-aged and elderly population, we used the logistic regression analysis to determine the odds ratios (OR), which reveal the at-risk levels of dyslipidemia." (PMID 34749748, 2021). "Mice that are deficient of apolipoprotein E show impaired lipoprotein clearance and when challenged with a high-fat high cholesterol diet have a rapid onset of metabolic risk factors, including steatosis, hepatic inflammation, insulin resistance, and dyslipidemia." (PMID 32796650, 2020). "Given that our findings confirm that genetic polymorphisms of APOE influence the inter-individual variation in total plasma cholesterol, a marker of dyslipidemia, changes in dietary consumption to reduce disease susceptibility could be implemented for individuals at genetic risk." (PMID 29712557, 2018). "The study aimed to assess whether the common APOE polymorphism is associated with lipid profiles and dyslipidemia, and it could be modulated by obesity-related traits (body mass index, waist circumference, hip circumference, and waist-to-hip ratio) in Vietnamese children." (PMID 27724906, 2016). "Thus, the apoE-deficient rats exhibited dyslipidemia in this study." (PMID 23295061, 2013).
dyslipidemia (continued). "We assessed the association between APOE genotypes and DPN susceptibility in patients with T2DM, focusing on dyslipidemia-linked pathways underlying neuropathy susceptibility distinct from glycemic effects." (PMID 41488146, 2025). "Our research findings confirm that the GLXB herb pair ameliorates dyslipidemia in ApoE-/-mice by reducing serum TC, TG, and LDL-C levels and elevated HDL-C." (PMID 41466480, 2025). "After 8 weeks of consuming a HFD, the ApoE−/− mice showed dyslipidemia, as indicated by marked increases in plasma TC, TG, and LDL‐C levels, as compared to C57 BL/6 mice fed a NFD." (PMID 39601316, 2025). "Metabolic syndrome was induced in APOE−/− and C57BL/6 mice using a high-fat, high-sugar diet, while psoriasis-like lesions were induced in the mice via the administration of imiquimod." (PMID 40417212, 2025). "A potential regulatory association between dyslipidemia-driven PPP2CB upregulation and ApoE was indicated." (PMID 40611318, 2025). "Our findings are consistent with these reports that Ruminococcaceae_UCG-014, Rikenella, and Ruminiclostridium are colonies that play a vital role in the regulation of dyslipidemia by the GLXB herb pair in ApoE-/- mice." (PMID 41466480, 2025). "Although ApoE−/− mice are characterized by dyslipidemia, numerous studies have indicated that a high-fat diet (HFD) exacerbates metabolic disturbances, thereby accelerating the pathological processes observed in this model." (PMID 40867851, 2025). "In conclusion, the GLXB herb pair exerts a therapeutic effect on dyslipidemia in ApoE-/- mice by decreasing intestinal cholesterol absorption in ApoE-/- mice by increasing the level of butyric acid, a metabolite of the gut microbiota." (PMID 41466480, 2025). "Dyslipidemia is one of the causes of coronary heart disease (CAD), and apolipoprotein E (APOE) gene polymorphism affects lipid levels." (PMID 38987708, 2024). "The goal of this study is to investigate the relationship between Apolipoprotein E (ApoE) genotypes, dyslipidemia, and cardiovascular complications such as ischemic heart disease (IHD) and stroke." (PMID 38929578, 2024). "In the present study, we observed that chronic quercetin treatment effectively improved HFD-induced dyslipidemia in ApoE KO mice, with a significant reduction in TC, TG, and LDL-C levels, as well as an increase in HDL-C levels." (PMID 39062998, 2024). "Their complicated functions were specified by comparing DEGs in PMN versus Ctrls: first, PMN samples showed increased expression levels of APOC1 and APOE in response to dyslipidemia in PMN." (PMID 38785168, 2024). "Few significant associations were found between the PCs and biochemical variables, such as plasma glucose levels and dyslipidemia, APOE genotype, disease status, and ATN classification." (PMID 39796148, 2024). "In summary, the APOE cKO and D374Y strains allow for inducible atherogenic dyslipidemia in adult mice, which results in rapid liver cholesterol and triglyceride accumulation that is not immediately apparent by histological or liver function analysis." (PMID 39196121, 2024). "Contradictory results were presented by an investigation demonstrating that VDR deletion protected against liver steatosis, dyslipidemia, and insulin resistance in apolipoprotein E (apoE) knockout (−/−) HFD mice." (PMID 38732118, 2024). "Our findings showed a decreased expression of the APOE gene in both AF subjects and those with metabolic syndrome compared to the control group." (PMID 39166676, 2024). "In this study, 16 weeks later, HFD‐induced weight gain and dyslipidemia were observed in ApoE−/− mice." (PMID 38628207, 2024). "ApoE polymorphisms are reportedly associated with the transcription level of ApoE, serum total cholesterol (TC), triglyceride (TG), HDL, LDL, and VLDL levels, as well as the risk of dyslipidemia." (PMID 37123009, 2023). "ApoE is an apolipoprotein that is involved in regulating lipoprotein metabolism and is important in dyslipidemia and CVD." (PMID 37372091, 2023).
dyslipidemia (continued). "Since high concentrations of certain lipid species have been linked with worsening of the metabolic syndrome and NASH, we sought to determine how the WTD affects the hepatic lipidomic profile in APOE*3-Leiden mice and how atorvastatin affects this profile." (PMID 37175538, 2023). "Among 5743 probands diagnosed with primary dyslipidemia (58% ADH and 42% FCHL), we identified a total of 76 carriers of a rare APOE variant (53% women, 48 ± 15 years old, LDL-MoM = 1.91 ± 0.56, TG-MoM = 2.10 ± 1.65)." (PMID 35628605, 2022). "APOE rs429358 and APOC1 rs438811 were also independently associated with metabolic syndrome (p = 2.29 × 10−14) and serum albumin levels (p = 3.80 × 10−6), respectively." (PMID 36011277, 2022). "Together, these results directly confirm the metabolic syndrome phenotype of yellow agouti KKAy+/–ApoE–/– mice, characterized by increased body weight, blood glucose and total cholesterol levels." (PMID 36505365, 2022). "In the current study, we concentrated on plasma triglyceride in combination with obesity and used MINGLeD to analyse which processes are altered during the progression of the metabolic syndrome in male APOE*3-Leiden.CETP mice on a high-fat diet." (PMID 36432620, 2022). "It was observed that decreased LPL expression seems to induce dyslipidemia as ApoE−/− mice had reduced levels of HDL-C and elevated levels of TAG as well as CHOL." (PMID 35883883, 2022). "Our data also indicated that APOE and APOC1 variants were independently associated with metabolic syndrome and serum albumin levels, respectively." (PMID 36011277, 2022). "Further studies showed that ApoE deletion altered the hippocampal metabolic profile and aggravated dyslipidemia and oxidative stress in aging mice." (PMID 36188475, 2022). "If dyslipidemia is resolved by transplanting the atherosclerotic aortic arches from apolipoprotein E (ApoE)−/− mice into healthy recipients or via dietary changes in regression models, CD68+ plaque macrophage numbers decrease." (PMID 34876704, 2022). "In this study, we found that the serum concentrations of TC, TG, and LDL were significantly increased in aging mice, while ApoE deletion aggravated dyslipidemia in aging mice." (PMID 36188475, 2022). "This study explored the genetic determinants of cardiometabolic traits and metabolic syndrome at the APOE locus in a Taiwanese population." (PMID 36011277, 2022). "Further studies are warranted to explore rs290487 and rs290481 influence on the other lipid fractions (VLDL, chylomicron, ApoE, etc.), to understand on how TCF7L2 gene polymorphisms influence on dyslipidemia." (PMID 35341056, 2022). "The association between APOE and APOC1 variants and metabolic syndrome and serum albumin levels further supported the crucial role of APOE region variants in cardiometabolic disorders in a Taiwanese population." (PMID 36011277, 2022). "In this study, we used apolipoprotein E knockout (ApoE-/-) mice to generate models of dyslipidemia with PDR or SKYD for matched and unmatched prescription-syndrome experiments." (PMID 35392646, 2022). "Clinically, high ApoE expressions are indicative of dyslipidemia, a condition characterized by elevated levels of TC and TG in the plasma." (PMID 34869779, 2021). "However, the final data showed the carrier of APOE ε2 could be a protective factor of dyslipidemia, while only in the elderly (65+) females, the APOE ε4 carriers might be a risk factor for high TG, which might limit the innovation of this study to a certain extent." (PMID 34749748, 2021).
dyslipidemia (continued). "The authors reported a protection of high fat diet-fed apoE−/− mice against fatty liver, dyslipidemia and insulin resistance due to deletion of the VDR." (PMID 34827697, 2021). "The range of atherosclerotic lesions in the aorta of ApoE−/− mice with dyslipidemia was significantly reduced in the treatment with NGM282 (the analog of FGF19)." (PMID 32528406, 2020). "Our findings indicated that 2 months of fructose intake, triggered metabolic derangements in spontaneously hypercholesterolemic ApoE-KO mice, mimicking MetS characterized by dyslipidemia, high insulin levels and hyperglycemia." (PMID 33154969, 2020). "Two months of fructose intake triggered metabolic derangements in ApoE-KO mice characterized by dyslipidemia, hyperglycemia and hyperinsulinemia." (PMID 33154969, 2020). "In order to explore the relationship between dyslipidemia and ApoE genotype, we divided the sample according to ApoE ε4 status (ε4+ and ε4−)." (PMID 32485802, 2020). "Apolipoprotein E knock-out (ApoE KO) mice are a metabolic syndrome model used in cardiovascular and non-alcoholic steatohepatitis research." (PMID 32796650, 2020). "Taken together, these results demonstrated that 2 months of fructose intake triggered metabolic derangements in spontaneously hypercholesterolemic ApoE-KO mice, which mimics human MetS characterized by dyslipidemia, high insulin levels and hyperglycemia." (PMID 33154969, 2020). "We found that the serum metabolic profile of dyslipidemia ApoE-/- mice was significantly different from that of the normal controls." (PMID 31269076, 2019). "HFD-fed ApoE-/- mice develop not only dyslipidemia and atheromatous lesions in the vascular tree but also many metabolic disturbances associated with CMS." (PMID 30818779, 2019). "Our study aimed to demonstrate the relationships among the statins response and the ApoE gene common polymorphisms and lifestyle risk factors in Chinese arteriosclerotic cardiovascular disease (ASCVD) patients with dyslipidemia." (PMID 31153375, 2019). "In the present study, we used ApoE−/− mice as an animal model because it is more apt to show the pathological changes of OSA-accompanying AS, such as inflammatory susceptibility, dyslipidemia and extracellular matrix degradation." (PMID 29673358, 2018). "This study aims to investigate the effects of leonurine (SCM-198) on dyslipidemia in mammals with ApoE knockout (ApoE-/-) mice, New Zealand white rabbits and senile Rhesus monkeys fed with high fat diet were dosed daily with leonurine or atorvastatin." (PMID 30618759, 2018). "In this study, we investigated the mechanism of GTP-induced autophagy and its role in accumulation of lipids in vascular endothelial cells, as well as in dyslipidemia in ApoE-knockout mice." (PMID 28777810, 2017). "Several studies have indicated that ApoE isoforms may be associated with obesity and its related disorders through direct and indirect effects on lipid metabolism and that obesity and dyslipidaemia play a pivotal role in the development of the metabolic syndrome." (PMID 28727855, 2017). "In this modern environment, the ABCA1, APOE (ε2 and ε4) and LCT polymorphisms have been associated with obesity, dyslipidemias, type 2 diabetes and other metabolic alterations." (PMID 29125573, 2017). "Corresponding with the dyslipidemia, we further observed an increased fatty ifiltration into hepatocytes, which would have resulted in hepatic lipid accumulation and steatosis, in ApoE-knockout mice when compared to the mice in the C57BL/Control group." (PMID 28777810, 2017).
dyslipidemia (continued). "The major finding of the present study is as follows: 1) Chronic METH treatment aggravated plasma dyslipidemia and atherosclerotic plaque formation in APOE−/− mice fed high cholesterol diet." (PMID 28903402, 2017). "The critical role of APOE in metabolic syndrome has been well documented in APOE gene knock-out mice." (PMID 27853276, 2016). "APOE variations have a well-established role in dyslipidemias yet incompletely defined contribution to FCH." (PMID 27227539, 2016). "Our results showed that apoE-/- mice receiving vehicle alone developed severe atherosclerotic lesions and dyslipidemia, with significantly up-regulated levels of IL-6, TNF-α, VCAM-1 and MCP-1." (PMID 24621517, 2014). "The goal of this study was to investigate the possible protective effects of sitagliptin against dyslipidemia-related kidney injury in apolipoprotein E knockout (apoE−/−) mice." (PMID 24972137, 2014). "ApoE−/− mouse is the classical modle of AS and dyslipidemia, characterized by high levels of plasma cholesterol and/or TG or low level of HDL, in addition, this mouse model indicates some incline to express fatty liver." (PMID 23497035, 2013). "A previous study using apoE KO mice analyzed the influence of genetic and high-fat/cholesterol diet-induced dyslipidemia on T cell and dendritic cell (DC) responses to L. major infection in vivo and, mainly, in vitro." (PMID 23710353, 2013). "Multivariate logistic regression analysis was performed to identify the associations of the APOE, SCARB1, PPARα genotypes with the prevalence of dyslipidemias in the study population." (PMID 23919842, 2013). "The purpose of this study was to investigate the effects of dyslipidemia on osteoclast differentiation associated with TLR2 and TLR4 in periodontal tissues using a rat dyslipidemia (apolipoprotein E deficient) model." (PMID 23295061, 2013). "Similar results were obtained in the research that up-regulation of pro-inflammatory cytokines like TNF-a, IL-6 and IL-12 were found in patients with dyslipidemia and in animal investigation of apoE−/− mice." (PMID 23472151, 2013). "According to these results, it appears that the therapeutic response of patients with dyslipidemia to sardilipin is APOE-related." (PMID 22482072, 2012). "We assessed individual apoE genotypes and lipid blood profile in a total of 463 patients followed at a specialized lipid clinic due to dyslipidemia, with a 3-year median follow-up time." (PMID 21450082, 2011). "The dramatic loss of hepatic SR-BI protein in the livers of Paigen diet-fed PDZK1/apoE KO mice clearly contributed to their dyslipidemia and possibly played a role to the relatively unusual murine early onset occlusive coronary artery disease." (PMID 19956623, 2009). "For animal experiments, we fed ApoE-/- mice a HFD to establish a model of dyslipidemia." (PMID 41466480, 2025). "Both findings underscore the role of dyslipidemia in APOE-related CVD development." (PMID 39364911, 2025). "Finally, the GLXB herb pair inhibited the expression of cholesterol absorption-related proteins by up-regulating the gut microbiota metabolite butyric acid in ApoE-/- mice, thus exerting anti-dyslipidemia effects in ApoE-/- mice." (PMID 41466480, 2025). "It has been reported that APOE isoforms are important genetic markers for dyslipidemia." (PMID 40026415, 2025). "In summary, we demonstrated that the GLXB herb pair could reduce serum TC, TG, and LDL-C levels in ApoE-/-mice and elevate HDL-C to improve dyslipidemia in ApoE-/- mice." (PMID 41466480, 2025). "Most have not targeted women at the highest risk—those with metabolic syndrome, cerebrovascular pathology, or APOE-ε4 genotype." (PMID 40661313, 2025). "The following characteristics seem to be associated with aggravated dyslipidemia: adulthood, male gender and homozygosity (as opposed to heterozygosity) for the APOE-ε1 allele." (PMID 40149441, 2025).